TNF (tumor necrosis factor)
Diseases named in the same sentence as TNF in open-access papers (continued):
Sharing a sentence is not in itself a finding about the gene and the disease.
tumor (continued). "Normally, the activation of CAR‐T cells in vivo will result in their killing of tumor cells accompanied with release of cytokines such as IL‐2, IFN‐γ, and TNF‐α." (PMID 31237116, 2019). "Essentially, interleukin 6 (IL6) and TGFβ promote tumor growth, IL6 together with TNFα facilitates invasion and metastasis, and TGFβ with IL10 suppresses the immune response against the tumor." (PMID 31921146, 2019). "In advanced tumor mouse models, TANs induce CD8 T-cell apoptosis via TNFα pathway and NO, and so do participate to the immunosuppressive response." (PMID 31799175, 2019). "TNF-α also mediated upregulation of GM2 in tumor cells and accelerated tumor-induced T cell apoptosis and immune dysfunction." (PMID 30761148, 2019). "By producing various cytokines including IFN-γ, tumor necrosis factor (TNF)-β, and interleukin (IL)-2, Th1 cells show a strong effect in repressing tumor growth, and IFN-γ possesses capabilities for anti-tumor effects and immunomodulation." (PMID 31038546, 2019). "SW480- and U87-MG-derived exosomes induce the release of IL-1α, IL-8 and MCP-1 by monocytes, while exosomes released from all tumor cell lines after LPS treatment trigger the production of IL1β, IL-10, IL-6, MIP-1α, MIP-1β and TNF-α cytokines." (PMID 31186484, 2019). "A treatment regimen with 5 daily doses of 2–5 μg TNFα‐CSG prolonged the survival of these mice, consistent with reduced 4T1 tumour burden and cancer cell proliferation (Ki67+ staining), and increased apoptosis (TUNEL+ cells)." (PMID 31709774, 2019). "The EBV-miRNA miR-BART19-5p, which we found elevated in tumor tissue, is shown to target its own gene LMP1, which is a functional homologue of tumor necrosis factor that can downregulate host miR-146a." (PMID 30786859, 2019). "Tumor immune evasion has been shown to occur through the suppression of antigen presentation and cytokine signaling, namely IFN-ɣ and TNF signaling." (PMID 30875739, 2019). "MAPK14 is an important apoptotic inducer, TNF-α, TGF-β and oxidative stress activate MAPK14 signaling pathway to induce apoptosis, and exert its anti-tumor effect." (PMID 31905767, 2019). "The ELISA quantification data indicated a down-regulation of pro-tumor cytokines (IL-10, VEGF-A, and TGF-β1) and an up-regulation of anti-tumor cytokines (TNF-α, IL-12 p70, and IFN-γ) in the acGM-1.8-treated group." (PMID 31118418, 2019). "This triple combination therapy improved T cell effector function in tumor bearing mice by increasing the proportion of tumor infiltrating CD4+ and CD8+ T cells that can produce both interferon gamma and TNF." (PMID 31052546, 2019). "The second wave of increased IL1β, TNFα, and IL6 expression is observed in the 5th day of tumor growth while IL10 second wave occurred two days earlier." (PMID 31712726, 2019). "These cells can secrete anti-tumor cytokines such as interferon (IFN)-γ, tumor necrosis factor (TNF)-α, IL-17, and IL-2." (PMID 30646912, 2019). "For example, TNF‐α stimuli always increases the expression of CXCR4 in malignant cells, which can promote tumor progression by direct and indirect mechanism." (PMID 31222971, 2019). "This “silver bullet” against cancer seemed close at hand in 1995 when tumor necrosis factor (TNF)-related apoptosis-inducing ligand (TRAIL/Apo2L) was introduced and later shown to selectively induce apoptosis in tumour cells in vivo." (PMID 30935038, 2019). "When treated with exosomal Hsp70 and Hsp72, MDSCs was found to significantly increase the production of pro-inflammatory cytokines including IL-6, TNF- α, VEGF, and CCL2, leading to an increase in tumor growth and metastasis." (PMID 31555295, 2019). "Having shown that TNFα‐CSG attracts immune cells to tumour ECM, we explored their potential role in tumour matrix degradation." (PMID 31709774, 2019).
tumor (continued). "However, besides inflammation, several studies implicate a role of TNFα signalling during tumour development and also infectious diseases, therefore anti-TNFα treatment might be a starting point for additional therapeutic strategies to cure intestinal diseases." (PMID 30995806, 2019). "Increases IFN-γ and higher numbers of tumor-infiltrating CD4+ lymphocytes.The generation of IL-6, IL-12, IL-23 and TNF-α in dendritic cells increases rapidly." (PMID 31083446, 2019). "Tumor necrosis factor-α (TNF-α) acts as a critical inflammatory factor that links inflammation and tumor, which is also correlated with angiogenesis, proliferation, invasion, and migration in human cancers." (PMID 31885751, 2019). "Further, it increased the production of interferon gamma (IFN-γ) and tumor necrosis factor alpha (TNF-α) by CD8+ T and NK cells in spleens as well as tumor microenvironment and increased the cytotoxic effects of CD8+ T and NK cells." (PMID 31817720, 2019). "Tumor hypoxia is thought to be important in the activation of TAM and promotes the release of TNF-α and VEGF." (PMID 31138333, 2019). "Of these molecules, IL-1β, IL-6, TNF-α, and IL-4 promote the phosphorylation of downstream proteins, e.g., NF-κB and STAT3, which then lead to inflammation, tumor proliferation, and prevention of apoptosis in cancer." (PMID 31781219, 2019). "It has been suggested that TNF expressed by macrophages can promote angiogenesis through IL-8 and VEGF to help tumor cells escape from immune system." (PMID 31118022, 2019). "NK cells can directly kill tumor cells, secrete various cytokines such as interferon (IFN)-γ and tumor necrosis factor (TNF)-α to initiate antitumor responses, and recruit other immune cells into the antitumor response." (PMID 31681269, 2019). "NK cells exert its function on pathogens, tumor cells, stressed hepatocytes, and HSCs via the production of cytokines (IFN-γ, TNF-α, IL-10, IL-12, IL-22, etc.)and cytotoxic molecules (granzyme B, Perforin, etc.)both in direct or indirect fashion." (PMID 31500589, 2019). "A reduction in pro-inflammatory cytokines, such as IL-6, TNF-α, and IFN-ɣ, was observed in mice treated with the triple combination, which suggests that a synergistic combination has significant effects against tumor progression." (PMID 31635311, 2019). "Multivariate analysis revealed that preoperative serum IL6 > 8.45 pg/ml, preoperative serum IL8 > 68 pg/ml, preoperative serum TNF − α > 14.9 pg/ml, microvascular invasion (MVI), and maximum tumor size > 6 cm were independent predictors of RFS." (PMID 31781194, 2019). "Aside from IFN-γ and TNF-α, cytotoxic mediators such as granzymes and TRAIL are produced by γδ T cell-subsets and used for killing a broad range of tumor cells." (PMID 31555275, 2019). "In our experimental model, enhanced secretion of IL-1β, PGE2, TNF-α, and IL-6 occurs following CRC cells/LSECs crosstalk in a tumor LFA-1/LSEC ICAM-1 interaction dependent fashion." (PMID 31511625, 2019). "VEGF and TNFα signalling disrupt EC barrier function via activation of PI3K/Akt signalling and tumour cells transmigrate through EC monolayers via induction of PI3K signalling in ECs." (PMID 31787905, 2019). "Do death factors TNF, FasL (Fas ligand) and TRAIL (TNF related apoptosis inducing ligand) play a role in the induction of tumor necroptosis?" (PMID 31922095, 2019). "The cytokines secreted by tumor cells, such as granulocyte colony-stimulating factor (G-CSF), interleukin (IL)1β, IL6 or tumor necrosis factor (TNF), have been suggested to extend their lifespan." (PMID 31408948, 2019). "In view of their high relevance to tumor progression in TNBC, TNFα and IL-1β were selected as representatives of the pro-inflammatory TME in our study." (PMID 31031757, 2019).
tumor (continued). "In a pro-inflammatory environment, i.e., under conditions of chronic inflammation, inflammatory mediators such as cytokines and chemokines (TGFβ, TNFα, IL1, IL6, IL8) produced by immune cells and MSC also induce tumor cell EMT and impact CSCs." (PMID 31557960, 2019). "The local inflammatory microenvironment can induce tumor cells to produce tumor-derived secreted factors (TDSFs), such as vascular endothelial growth factor (VEGF), tumor necrosis factor alpha (TNF-α), transforming growth factor-β (TGF-β) and interleukin (IL)." (PMID 30857545, 2019). "Many cytokines produced during tumor growth, such as interleukins (ILs), vascular endothelial growth factor (VEGF) and tumor necrosis factor (TNF), stimulate the production of granulocytes and platelets." (PMID 30961549, 2019). "In the COS-treated CRC group (CMCOS), COS protected mice from CRC by decreasing the disease activity index, tumor incidences and multiplicity, and the mRNA levels of COX-2, IL-6, TNF-α, IL-1β, IL-10, and IKK-β mRNA in colonic epithelial cells." (PMID 31620100, 2019). "However, the robust anti-tumor activity displayed by these CAR T cells was associated with induction of cachexia in animal models that requires specific strategies to reduce cytokine toxicity, such as administration of anti-TNFα antibody or selection of low cytokine producing T lymphocytes." (PMID 31547472, 2019). "Data from our study suggests IT-101 has the potential to activate NK cells to inhibit tumor spread and induce subsequent immunity by secreting activated cytokines such as IFN-γ and TNF-α." (PMID 31647037, 2019). "TNFα‐CSG therapy was ineffective in BALB/c nude mice, and transfer of normal CD8+ and CD4+ T cells into these mice restored the ECM degradation and anti‐tumour effects." (PMID 31709774, 2019). "Subsequently, a wave of growth factors such as EGF, basic and acidic FGF, estrogen, prostaglandin E1 and E2, IL-8, TGF, TNF, neuropilins, and VEGF promotes the formation of a vascular network that ensures the exchange of oxygen and nutrients with the tumor." (PMID 31921634, 2019). "We began this part of the study by asking which of the two cell types, the MSCs and/or the tumor cells, contribute/s to CXCL8 expression in TNFα-stimulated MDA-MB-231:MSC “Contact” co-cultures." (PMID 31105691, 2019). "Systemic IgE treatment in this model was also associated with a specific cytokine signature, featuring elevated levels of TNFα, MCP-1 and IL-10 in the tumour microenvironment and upregulated expression of TNFα by tumour-associated macrophages in rat lungs." (PMID 30956175, 2019). "CD56dimCD16− subset showed the highest level of CD107a expression as well as the biggest amount of TNF-α and IFN-γ secretion compared to other subpopulations, suggesting their crucial role in the anti-tumor capacity of the NK cells." (PMID 30949182, 2019). "To study the potential therapeutic effects of TNFα‐CSG, we first assessed the survival of RIP1‐Tag5 and 4T1 tumour‐bearing mice." (PMID 31709774, 2019). "We also compared the expression levels of perforin, granzyme B, IFN-g, TNF-a, and IL-2 of CD8+ T cells between PBMCs and tumor in each T cell subset." (PMID 30682105, 2019). "In both OSCC animal models, SCNE significantly depressed circulating pro-cancer inflammatory cytokines (host and tumor-secreted) including NFkB, COX2, IL-1, IL-6, TNFα, and IFNγ." (PMID 31572681, 2019). "The two key functions of natural killer (NK) cells are cytotoxicity against tumor and virus-infected cells and the production of cytokines and chemokines, such as interferon-γ (IFN-γ) and tumor necrosis factor-α (TNF-α)." (PMID 30925759, 2019). "TNF-α, IL-6 and TGF-β promote the production of IL-17 which affects chronic inflammatory responses and thus tumor development." (PMID 30642295, 2019). "CX3CL1 is a chemokine induced by inflammatory cytokines such as TNFα, IL-1β, and IFN-γ and its role is to recruit immune cells at tumor sites and to boost antitumor immune responses." (PMID 30108590, 2018).
tumor (continued). "Under conditions of chronic inflammation, such as cancer, MDSCs are released from the bone marrow and undergo continuous expansion in response to tumor secreted-growth factors such as MCSF, VEGF, TNF-α, and IL-6." (PMID 29805773, 2018). "Cytokine levels relative to tumor characteristics were assessed for VEGF, MCP-1, PAI-1, TNF-α, IL-6, transforming growth factor- (TGF-) β, and IL-10 by ELISA at the end of 72 h of coculture." (PMID 30034291, 2018). "A recent study in Drosophila showed that Wg dependent tumours proliferate independently of the TME and TNF-α/Grnd." (PMID 29725601, 2018). "The presence of cytokines in the ACP tumours was also assessed by multiplex ELISA against IL1B, IL6, IL8 (CXCL8), IL10, IL18, TNF (TNFα) and IFNG (IFNγ), which revealed the expression of all of these but IFNG in protein lysates from eight human ACPs." (PMID 29541918, 2018). "Activated γδ T cells exhibit potent anti-tumor activity by releasing copious amounts of IFN-γ and TNF-α." (PMID 29765907, 2018). "Beyond tumor growth, we also detected several DEGs enriched in metastasis, including vinculin (VCL) and Tumor necrosis factor (TNF) receptor superfamily member 12A (TNFRSF12A)." (PMID 30301189, 2018). "LCMV-specific CD8+ T cells and tumor infiltrating lymphocytes from IFNARfl/flxFoxp3YFP-Cre mice produced less antiviral and antitumor IFN-γ and TNF-α." (PMID 29672594, 2018). "(A) Flow cytometry analysis of the TNF-α and IFN-γ production of tumor-infiltrating CD8+ effector T cells cocultured with tumor-infiltrating TIM-1+ B cells or TIM-1− B cells." (PMID 30526680, 2018). "This study established down-regulating expression of membrane antigens that are indicative of the activation, differentiation, and maturation of tumor Jurkat T cells (CD3, CD4, CD8, and CD95) and reducing the secretion of IL-4 and TNFα." (PMID 29495627, 2018). "We have previously reported that a cell therapy product consisting of monocyte-derived DC loaded with heat-treated autologous tumor lysate and matured with a cocktail of poly-ICLC, TNFα and IFNα was immunogenic." (PMID 30268156, 2018). "The serum levels of both IL-6 and TNF-α level was found to be substantially higher in untreated tumor bearing mice whereas both CSL and bortezomib treated group had decreased levels of IL-6 and TNF-α as compared to control group." (PMID 29773987, 2018). "To more closely mimic the proinflammatory tumor microenvironment (TME), we assessed the ability of macrophage-derived TNFα to induce apoptosis in the context of IAP inhibition." (PMID 30349042, 2018). "For example, MyD88 was shown to promote tumor growth in the MCA-induced fibrosarcoma model, while simultaneously mediating a protective host response via TNFα and IFN-α/β signaling." (PMID 30150983, 2018). "As an immune-activating factor, HMGB1 released from necrotic tumor cells binds to Toll-like receptor 4 (TLR4) expressed by dendritic cells (DCs) to promote antigen presentation and also activates macrophage TNF release and thus activates antitumor immunity." (PMID 30643519, 2018). "In cancer, once the tumor cell is recognized, NK cells trigger their own cytotoxic activity or release cytokines and recruit other immune cells by IFN-γ and tumor necrosis factor-alpha (TNF-α) secretion." (PMID 29755647, 2018). "The expression of PD-L1 on tumor cells is induced by EMT, IFN-γ, tumor necrosis factor-α (TNF-α), and EGF in the inflammatory tumor microenvironment." (PMID 30126206, 2018). "Our study indicated that OMT in combination with DDP significantly upregulated the production of IFN-γ and TNF-α in CD8+ T cells compared with the single agent both in the splenocytes and tumor infiltrating lymphocytes." (PMID 30619765, 2018). "In tumors, it was proposed that TNF-α signaling through TNFR2 inhibits caspase 8 activity and promotes MDSC survival and accumulation helping tumor cells to evade the immune system." (PMID 30123776, 2018).
tumor (continued). "Under chronic inflammatory conditions, tumor necrosis factor alpha (TNF-α), secreted mostly by macrophages, led to PD-L1 stabilization and therefore to an immunosuppressive profile of the tumor environment." (PMID 29765155, 2018). "Next to STAT3, NF-κB is known to regulate the expression of many tumor-promoting genes, including VEGF, IL-6, TNF-α, and cyclooxygenase 2 (COX2), which support its crucial role in the activation of TAM2 in the TME." (PMID 30233579, 2018). "It is reported that NPM1 is associated with nuclear NF-κB p65 to enhance the DNA binding activity of NF-κB in response to TNF-α stimulation, and that NPM1 and NF-κB are likely to act cooperatively to regulate tumor progression." (PMID 29535419, 2018). "We show that high and intermediate HER2-expressing cancer cell lines are driven toward apoptosis and tumor senescence when treated with either CD4+ Th1 cells, or Th1 cytokines TNF-α and IFN-γ, in a dose dependent manner." (PMID 29796172, 2018). "In previous studies, TGFβ1 and TNFα, either alone or in combination, have been used to experimentally induce EMT in various epithelial tumor cell types including NSCLC cells." (PMID 30356176, 2018). "Our results are in agreement with a previous study in which higher expression of IL-2, TNF-α, and granzyme B in CAR T cells was also observed, when similarly made CAR T cells were co-cultured with target tumor cells with EGFR or EGFRvIII." (PMID 29685162, 2018). "Furthermore, it has been demonstrated that an abnormal elevation of serum or tumor-local inflammatory cytokines, including tumor necrosis factor; interleukin -1, -6, and -8; and vascular endothelial growth factor, could contribute to cancer progression by promoting tumor growth and metastasis." (PMID 29300750, 2018). "Since we found a downregulation of the TNFR II but an unaltered expression of TNFR I in tumor bearing STAT1 KO mice, it is notably that the transmembrane form of TNFα is able to exerts its cytotoxicity via both receptors." (PMID 30647851, 2018). "The treatment led to a significantly higher level of cytokines, such as TNF-α and IFN-β; thus, the growth of primary tumor was significantly inhibited." (PMID 30406152, 2018). "Although the most commonly studied cytokines regulated by MK2 are IL-1β, IL-6, and TNF-α, here we showed that MMM are also substantially decreased in tumor cells and in tumors with mixed cell populations upon MK2 inhibition." (PMID 30298062, 2018). "The tumor suppressive effects of M1 TAMs were augmented by Chondramide via activation of SAPK/JNK and NFκB pathways and elevated TNFα production." (PMID 30467396, 2018). "The secretion of cytokines (primarily TNF-α and IFN-γ) is one of the mechanisms by which CTLs kill tumor cells." (PMID 29435173, 2018). "Mice with tumors had elevated levels of inflammatory cytokines including IL-1α, IL-6, MIP-1α and G-CSF and lower levels of TNFα and CXCL1 compared to non-tumor bearing mice (all p < 0.05; statistics are provided in S1 Table)." (PMID 30532184, 2018). "A series of cytokines such as IL12, GM-CSF, IFN-α and tumor necrosis factor (TNF-α) used with oHSV can modify and enhance the anti-tumor immunity." (PMID 30563466, 2018). "While the accumulation of MDSC in inflammatory states was initially associated with increased TNFα and IL-6 levels, more recent data suggest that increased TNFα expression in the tumor microenvironment reduces MDSC infiltration and supports tumor regression." (PMID 29632539, 2018). "Other papers proved that systemic IL-17, through activation of the IL-6/Stat3 pathway and release of MMP2/9, TNF-α, and vascular endothelial factor (VEGF), induces tumor cell migration and metastatic growth in lung cancer-bearing mice." (PMID 30200242, 2018). "Strikingly, already 1 h after intraperitoneal injection, TNF-α levels increased, leading to the subsequent decrease of LLC tumor growth." (PMID 30349530, 2018).